ATF3 (activating transcription factor 3)
Diseases named in the same sentence as ATF3 in open-access papers (continued):
Sharing a sentence is not in itself a finding about the gene and the disease.
atherosclerosis (26 papers, 2014 to 2025). A disease characterized by the build-up of fatty material and calcium deposition in the arterial wall resulting in partial or complete occlusion of the arterial lumen. "The suppressed ATF3 expression in the liver is implicated in the exacerbated effects of ADF on atherosclerosis in these mice." (PMID 38736615, 2024). "ATF3 has been linked to atherosclerosis in different tissues and discussed as a potential biomarker and protective factor against atherosclerosis." (PMID 36144244, 2022). "The transcription factor activating transcription factor 3 (ATF3) was identified as a key regulator of a liver network relevant to atherosclerosis and linked to inflammation and cholesterol metabolism." (PMID 36144244, 2022). "Dysregulation of the common stress responsive transcription factor ATF3 has been causally linked to many important human diseases such as cancer, atherosclerosis, infections, and hypospadias." (PMID 27146783, 2016). "Further, a variety of stress-stimuli, which are also known risk factors for the development of atherosclerosis, can rapidly induce ATF3 in endothelial cells." (PMID 26709509, 2015). "It was recently shown that unfolded protein response and ATF3 are associated with inflammation response related to atherosclerosis in endothelial cells." (PMID 24993133, 2014). "The importance of ATF3’s immunosuppressive function is highlighted in several the disease models where a loss of ATF3 is detrimental including endotoxic shock, atherosclerosis, and ischemia reperfusion injury." (PMID 37033378, 2023). "ATF3 has been implicated in the pathogenesis of atherosclerosis and may exert both inhibitory and stimulatory effects on the development of endothelial dysfunction." (PMID 37189834, 2023). "In addition to the regulation and suppression of antioxidant enzymes, ATF3 has also been implicated in the control of several other genes associated with the development of atherosclerosis, such as the expression of the adhesion molecule E-selectin and the cytokine IL-8 by our group and others." (PMID 26709509, 2015). "In the present study, miR-486 was predicted to target ATF3, which plays complex roles in cardiovascular pathogenesis (e.g., atherosclerosis, hypertrophy) and protection, underscoring its involvement in cardiac adaptation and stress responses." (PMID 41301959, 2025). "The suppressed ATF3 expression in the liver mediates the deteriorated effects of ADF on atherosclerosis in Apoe−/− mice." (PMID 39872376, 2024). "In this context, ATF3 is considered a novel prognostic biomarker and therapeutic target in atherosclerosis." (PMID 37189834, 2023). "Here, we summarize the roles of ATF3 in cellular lipid metabolism and the progression of atherosclerosis." (PMID 36472556, 2023). "Through investigating gene regulatory networks in atherosclerosis, these studies predicted MAFF/Maff and ATF3/Atf3 to orchestrate a liver network enriched in genes linked to atherosclerosis." (PMID 37000167, 2023). "Deletion of ATF3 in ApoE–/– mice fed a high-fat diet led to increased foam cell formation and macrophage inflammation during the progression of atherosclerosis by elevating aortic 25-hydroxycholesterol (25-HC) levels." (PMID 36472556, 2023). "With a focus on the development of atherosclerosis, ATF3 plays a crucial role in a multitude of pathophysiological changes, such as extracellular matrix dysfunction, smooth muscle cell proliferation and migration, and foam cell formation." (PMID 36144244, 2022). "In summary, this study provides novel insights identifying ATF3 as a central regulator of an atherosclerosis relevant liver network that is closely related to inflammation and cholesterol metabolism." (PMID 36144244, 2022).
atherosclerosis (continued). "In line with the LPS-induced ATF3 upregulation, ATF3 expression has been subject to metabolic, inflammatory and atherosclerosis research before." (PMID 36144244, 2022). "This study demonstrates that the transcription factor ATF3 is a significant key regulator of a dense liver network interacting with a large number of genes known to affect atherosclerosis in humans and mice." (PMID 36144244, 2022). "Elevated ATF3 expression due to different stimuli can damage endothelial cells to promote atherosclerosis." (PMID 36704356, 2022). "In an atherosclerosis model, ATF3 also exaggerates neointimal proliferation by enhancing VSMC proliferation." (PMID 33230462, 2020). "Sortilin promotes inflammation and consequently activates an autoregulation loop by ATF3 activation, although only few studies, all focused on atherosclerosis, confirmed the important role of sortilin/ATF3 axis in innate immunity." (PMID 30666202, 2018). "The ATF3 role in endothelial dysfunction and atherosclerosis is controversial." (PMID 39050921, 2024). "ATF3 can be a crucial therapeutic target molecule for the regulation of lipid metabolism and inflammation in the vascular wall to prevent the progression of atherosclerosis." (PMID 36472556, 2023). "However, others showed that ATF3 promotes ECs death in atherosclerosis, LPS induced inflammatory responses, and pro-inflammatory genes-E-selection and intercellular cell adhesion molecule 1 expression." (PMID 32826874, 2020). "ATF3 inhibits intestinal lipid absorption, enhances hepatic triglyceride hydrolysis and fatty acid oxidation, promotes macrophage reverse cholesterol transport, and attenuates the progression of western diet-induced nonalcoholic fatty liver disease and atherosclerosis." (PMID 36472556, 2023). "However, the regulatory capacities of ATF3 on atherosclerosis relevant pathways remain incomplete." (PMID 36144244, 2022). "The current evidence shows that ATF3 can regulate cell dysfunction, such as apoptosis and inflammation, but whether ATF3 is a mediating factor or an inhibitory factor is still unclear, and the specific mechanism of ATF3 in atherosclerosis is still unclear." (PMID 34320932, 2021). "Therefore, we will use animal and cell models to further verify whether the deletion or over expression of ATF3 depends on the NF-κB signalling pathway to regulate the inflammatory response in atherosclerosis." (PMID 34320932, 2021). "ATF3, an immediate, early transcription factor gene belonging to the activated protein 1 (AP-1) family, plays an important role in inflammation and infectious diseases, endoplasmic reticulum stress, mitochondrial oxidative stress, endothelial dysfunction, and prevention of atherosclerosis." (PMID 35087573, 2021). "Activating transcription factor 3 (ATF3) is an early response gene that is activated in response to atherosclerotic stimulation and may be an important factor in inhibiting the progression of atherosclerosis." (PMID 34320932, 2021). "Thus, ATF3 may maintain the survival of endothelial cells during vascular inflammation and atherosclerosis." (PMID 30404616, 2018). "We also observed that hepatocellular ATF3 expression was regulated by the cellular ISR pathway, and hepatocyte-specific overexpression of Atf3 in Apoe−/− mice weakened the effects of ADF on cholesterol profiles and atherosclerosis." (PMID 39872376, 2024). "In ECs, antisense ATF3/LRF-1 cDNA has been found to partially suppress the cell death induced by TNFα, ox-LDL, and lysophosphatidylcholine, which slows the progression of atherosclerosis." (PMID 36472556, 2023). "Activating transcription factor 3 (ATF3) belongs to the ATF/cAMP-responsive element-binding protein (CREB) family and is involved in the pathogenesis of various diseases, such as cancer, atherosclerosis, infections, and hypospadias." (PMID 35408860, 2022).
atherosclerosis (continued). "Functional regulatory networks identified ATF3 as a central regulator of an atherosclerosis relevant liver network based on candidate genes from human CAD GWAS and atherosclerosis relevant genes validated in genetically engineered mouse models." (PMID 36144244, 2022). "ATF3 is a member of the CREB/ATF family, participating in the development of cancer, atherosclerosis, hypertension, and ischemic heart diseases." (PMID 32826874, 2020). "In hepatocytes, endoplasmic reticulum stress induces an increase of ATF3 and thus a reduction of sortilin expression, leading to reduced VLDL clearance and promoting atherosclerosis." (PMID 30666202, 2018). "Fosb and Jun have specific roles in mediating cellular and arterial contractility, Atf3 is a CAD GWAS gene and has recently been identified to have vascular protective effect in atherosclerosis, and Klf4 has critical roles in mediating SMC phenotypic modulation and promotes atherosclerosis." (PMID 40931195, 2025). "However, whether ATF3 is a promoter or inhibitor has not been determined, and its role and mechanism in atherosclerosis are not clear." (PMID 34320932, 2021).
Sepsis (26 papers, 2013 to 2025). Sepsis is defined as life-threatening organ dysfunction caused by a dysregulated host response to infection. "The mRNA-binding protein AUF1 reduces sepsis-associated ALI damage by negatively affecting ATF3 and positively regulating Nrf2, which in turn controls ferroptosis." (PMID 40766305, 2025). "Previous study has demonstrated that ROS-induced ATF3 potentiates susceptibility to secondary infection in sepsis." (PMID 38395749, 2024). "Taken together, these data suggest that ATF3/ILF3/NEAT1 axis is implicated in M2 polarization in CLP-induced sepsis model." (PMID 38395749, 2024). "Due to immunosuppression associated with ATF3-mediated sepsis, ATF3 knockout mice exhibit longer survival than wild-type mice after infection with E. coli." (PMID 38255898, 2024). "ATF3 appears to play a complex central role in modulating pro-inflammatory responses as ATF3 deficient mice are more susceptible to sepsis and ventilator induced lung injury." (PMID 26709509, 2015). "In addition, ATF3 induction during sepsis augments susceptibility to secondary infections." (PMID 24062788, 2013). "For example, Circexoc5 enhances ferroptosis and exacerbates sepsis-induced ALI via the IGF2 BP2/ATF3 signaling pathway." (PMID 40811488, 2025). "A previous study revealed that ATF3 triggers M2 macrophage polarization to protect against inflammatory injury during sepsis via the ILF3/NEAT1 axis." (PMID 41181154, 2025). "ATF3 triggers M2 macrophage polarization to protect against the inflammatory injury of sepsis through ILF3/NEAT1 axis." (PMID 38395749, 2024). "In consistent with previous findings, we demonstrated that ATF3 was decreased in PBMCs derived from patients with sepsis and in LPS-stimulated RAW264.7 cells." (PMID 38395749, 2024). "In the current study, we reported that ATF3 protected against sepsis-induced ALI by promoting M2 polarization via ILF3/NEAT1 axis, shedding light on the targeted therapeutic strategies for sepsis." (PMID 38395749, 2024). "In summary, we reported that ATF3 triggered M2 macrophage polarization to protect against sepsis-induced lung injury through ILF3/NEAT1 axis." (PMID 38395749, 2024). "Activating transcription factor 3 (ATF3) promotes M2 polarization, however, the biological effects of ATF3 on macrophage polarization in sepsis remain undefined." (PMID 38395749, 2024). "In vitro functional experiments and in vivo studies in cecal ligation and puncture (CLP)-induced sepsis model revealed that ATF3 facilitated M2 polarization in sepsis via ILF3/NEAT1 axis." (PMID 38395749, 2024). "Increased urinary exosomal NGAL and activating transcription factor 3 in sepsis-induced AKI patients." (PMID 32082158, 2019). "Given that ATF3 KO mice displayed elevated procalcitonin levels, these data support the use of this factor as a sepsis biomarker." (PMID 30214444, 2018). "ATF3 can block the processes of innate immune response induced by invading pathogens in the early stage but also regulate the late-acting mediators of sepsis, such as HMGB1." (PMID 24062788, 2013). "The level of ATF3 in the lung tissues of a mouse sepsis model was measured to identify the role of ATF3 in LPS-induced sepsis." (PMID 24062788, 2013). "The preceding observations suggest that restoration of ATF3 expression in ATF3 knockout mice would be expected to reduce LPS-induced sepsis injury in these mice." (PMID 24062788, 2013). "ATF3 (urinary exosomal activating transcriptional factor 3) is a key regulator of the stress response and has been shown to play a role in ischemia–reperfusion injury and sepsis-induced AKI." (PMID 40155515, 2025). "The ATF3/ILF3/NEAT1 axis ameliorated sepsis-induced ALI via modulating M2 polarization." (PMID 38395749, 2024).
Sepsis (continued). "Another study revealed that naringenin protects against sepsis-related lung damage through AMPK-activating transcription factor 3 (ATF3)-dependent negative regulation of the LPS/TLR4 signaling pathway, suppressing the expression of TNF-α, IL-6, TLR4, iNOS, cyclo-oxygenase-2 (COX2), and NOX2." (PMID 39126050, 2024). "For instance, all target of ATF3 in PBMC treated with sepsis plasma were up-regulated." (PMID 30086151, 2018). "In addition, ATF3 expression was rapidly induced in the lung at 4 and 6 hpi, suggesting that ATF3 plays an important role in sepsis via IL-17A." (PMID 30214444, 2018). "As such, ATF3 KO mice exhibit prolonged survival over WT controls following infection with gram-negative bacteria owing to the induction of ATF3-mediated sepsis-associated immunosuppression." (PMID 30214444, 2018). "Inhibition of inflammation and blockade of HMGB1-TLR 4 vicious circle by ATF3 during endotoxemia may prevent patients from sepsis-mediated mortality." (PMID 24062788, 2013). "Therefore, suppressing LPS-induced inflammation with ATF3 induction will be an important target in pharmacologic treatment of sepsis." (PMID 24062788, 2013). "However, the biological effects of ATF3 on macrophage polarization in sepsis remain largely unknown." (PMID 38395749, 2024). "For instance, the upregulation of circEXOC5 exacerbated sepsis-induced acute lung injury (ALI) by stimulating ferroptosis through insulin-like growth factor-2 mRNA-binding proteins 2 (IGF2BP2) recruitment for degrading activating transcription factor 3 (ATF3) mRNA." (PMID 39769377, 2024). "Therefore, suppressing LPS-induced inflammation with ATF3 induction or ATF3 mimetics may be an important strategy for sepsis therapy." (PMID 24062788, 2013). "A recent study has demonstrated that AUF1 inhibits ferroptosis to ameliorate sepsis-induced ALI through modulating NRF2 and ATF3, suggesting that ATF3 also exerts its protective role in sepsis-induced ALI by regulating ferroptosis." (PMID 38395749, 2024). "Western blot revealed the decreased expression of ATF3, alone with the increased expression of ILF3 in the PBMCs derived from patients with sepsis." (PMID 38395749, 2024). "To investigate the biological roles of ATF3/ILF3/NEAT1 axis, we first examined the expression of these molecules in sepsis." (PMID 38395749, 2024). "In sepsis-induced lung injury, AUF1 modulates NRF2 and Atf3, impacting cellular oxidative stress and iron balance." (PMID 38254192, 2024). "In the sepsis-AKI setting, urinary ATF3 increased at the same days of increased serum creatinine which demonstrated the benefit of urinary AFT3 over urinary NGAL in predicting AKI." (PMID 35203344, 2022). "Another study by revealed that intraperitoneal injection of 10 mg/kg quercetin protected murine sepsis by inducing macrophage M2 polarization via the TRPM2 dependent calcium influx and AMPK/ATF3 activation." (PMID 36588685, 2022). "Together, these results indicate that ATF3 can reduce MCP-1 expression and decrease lung injury after sepsis occurrence in mice." (PMID 24062788, 2013). "Urinary ATF3 may therefore be a new biomarker for identifying renal tubular cell injury in early AKI and AKI in sepsis." (PMID 40370722, 2025). "Our findings might unravel a specific ATF3/ILF3/NEAT1 mechanism and provide promising therapeutic targets and profound implications for targeted therapy of sepsis." (PMID 38395749, 2024). "However, the mechanisms of ATF3 and the role of HMGB1 in regulating innate immunity-induced sepsis are incompletely understood." (PMID 24062788, 2013). "Therefore, ATF3 KO mice showed longer survival times than WT controls after infection with Gram-negative bacteria due to the induction of ATF3-mediated sepsis-related immunosuppression on the major reactive oxygen species (ROS) condition." (PMID 35370996, 2022).
Sepsis (continued). "ATF3 presents in the early stage (3 hrs) of endotoxemia to prevent macrophage activation and inhibit NO, IL-6, and TNF-α release that eventually will trigger an uncontrolled systemic inflammatory response that may lead to sepsis." (PMID 24062788, 2013). "Since ATF3 modulates the secretion and release of HMGB1, which is a down-stream proinflammatory mediator and may more closely reflect the status of sepsis, we, therefore, examined its level in sepsis patients." (PMID 24062788, 2013). "ATF3 was found earlier than sCr in the urine of patients with AKI, but not in normal persons, sepsis patients without AKI, or patients with CKD." (PMID 40370722, 2025). "For sepsis-induced AKI, a specific transcriptional repressor for activating transcription factor 3 (ATF3) was increased but not detected in the non-AKI group." (PMID 34471412, 2021). "Urinary ATF3 did not increase before serum creatinine, urinary ATF3 but not urinary NGAL would be a good additive biomarker for supporting the onset of AKI in sepsis condition with only a subtle increase of serum creatinine, including leptospirosis related AKI." (PMID 35203344, 2022).